MIR153-1 (microRNA 153-1)
Synonyms: hsa-mir-153-1; MIRN153-1; mir-153-1
Gene: MicroRNA gene on chromosome 2 (219,294,111 to 219,294,200, reverse strand). Ensembl gene ENSG00000207647.
Gene Ontology:
Cellular component: RISC complex
Homologues: Orthologues: chimpanzee MIR153-1 (94% identical), macaque mml-mir-153-1 (94% identical), pig MIR153-1 (91% identical), zebrafish mir153c (80% identical), zebrafish mir153b (76% identical). Paralogues in human: MIR153-2 (76% identical).
Diseases named in the same sentence as MIR153-1 in open-access papers:
MIR153-1 is named in the same sentence as 2 diseases in open-access papers, as found by Europe PMC text mining. Sharing a sentence is not in itself a finding about the gene and the disease.
MIR153-1 shares sentences with these, for which no sentence is quoted: cancer (1 paper); pancreatic cancer (1).